DPY19L1P1 (DPY19L1 pseudogene 1)
Gene: Transcribed unprocessed pseudogene on chromosome 7 (32,580,949 to 32,761,787, reverse strand). Ensembl gene ENSG00000229358.
Diseases named in the same sentence as DPY19L1P1 in open-access papers:
DPY19L1P1 is named in the same sentence as 1 disease in open-access papers, as found by Europe PMC text mining. Sharing a sentence is not in itself a finding about the gene and the disease. The quoted sentences say what the papers report.
Cryptococcal meningitis (1 paper, 2019). Meningeal inflammation produced by cryptococcus neoformans, an encapsulated yeast that tends to infect individuals with acquired immunodeficiency syndrome and other immunocompromised states. "Then, the receiver operating curves (ROC) were drawn for evaluating the diagnostic potential of DPY19L1p1 for cryptococcal meningitis, which revealed that DPY19L1p1 was able to discriminate between patients and healthy controls with an AUCROC of 0.9389; P < 0.0001." (PMID 30767376, 2019). "LncRNA DPY19L1p1 was found to be highly expressed in cryptococcal meningitis patients via PCR validation and tended to decrease after antifungal treatment." (PMID 30767376, 2019). "The expression of the lncRNAs, ECRP, LINC00968, DPY19L1p1, DEFA8P, and DEFT1P2 was higher but the expression of the lncRNAs DDX11L10 and MTMR9LP was lower in cryptococcal meningitis patients than in healthy controls, which was consistent with the chip analysis results." (PMID 30767376, 2019).